RN7SL761P (RNA, 7SL, cytoplasmic 761, pseudogene)
Gene: Miscellaneous RNA gene on chromosome 13 (68,693,804 to 68,694,081, reverse strand). Ensembl gene ENSG00000243671.
Homologues: Orthologues: chimpanzee Metazoa_SRP (97% identical), macaque Metazoa_SRP (91% identical), dog Metazoa_SRP (63% identical). Paralogues in human: RN7SL1 (76% identical), RN7SL2 (74% identical), RN7SL296P (74% identical), RN7SL3 (74% identical), RN7SL566P (74% identical), RN7SL7P (73% identical), RN7SL126P (73% identical), RN7SL127P (73% identical), RN7SL230P (73% identical), RN7SL397P (73% identical), RN7SL655P (73% identical), RN7SL278P (73% identical), and 701 more.